ALOX12 (arachidonate 12-lipoxygenase, 12S type)
Diseases named in the same sentence as ALOX12 in open-access papers (continued):
Sharing a sentence is not in itself a finding about the gene and the disease.
colon adenocarcinoma (1 paper, 2022). "The ALOX12 mRNA expression could be a diagnostic marker for colon adenocarcinoma and the expression of ALOXE3 combined with ALOX12 could have a prognostic value in colon adenocarcinoma." (PMID 35928873, 2022). "Finally, they reported that ALOXE3 and ALOX12 might serve as potential independent prognostic indicators of colon adenocarcinoma." (PMID 35928873, 2022).
diabetic cardiomyopathy (1 paper, 2018). Diabetic cardiomyopathy is a disorder of the heart muscle in people with diabetes. "In the heart, cardiac Alox12/15 has been reported to stimulate cardiac cell growth and is involved in cardiac dysfunction and fibrosis in diabetic cardiomyopathy." (PMID 29772700, 2018).
esophageal squamous cell carcinoma (1 paper, 2024). Esophageal squamous cell carcinoma (ESCC) is a type of esophageal carcinoma (EC) that can affect any part of the esophagus, but is usually located in the upper or middle third.
glioblastoma (1 paper, 2023). The most malignant astrocytic tumor (WHO grade IV). "ALOXE3 was reported to induce ferroptosis similar to ALOX12 in glioblastoma (GBM) cells." (PMID 37386007, 2023).
Hyperoxaluria (1 paper, 2021). Increased excretion of oxalates in the urine. "To confirm the in vitro observations of tubular inflammation, we then investigated the pro-inflammatory role of the ALOX12/TRPV1 pathway in the in vivo rat model of hyperoxaluria." (PMID 34201387, 2021). "Because there were parallel changes in TRPV1, ALOX12, and NLRP3 expression as well as caspase-1 activation and IL-1β formation in HP kidneys, we examined whether inhibition of TRPV1 would ameliorate hyperoxaluria-induced renal inflammation and tubular injury." (PMID 34201387, 2021).
kidney damage (1 paper, 2024). "Renal tubular ALOX12 protein levels were positively correlated with lipid metabolism indicators, including TC, HDLC, LHDL, and Apo B. ALOX12 was also positively correlated with indicators of kidney damage, including U-RBP, U-CYC, and U-ACR, where U-RBP is an indicator of renal tubular damage." (PMID 38345057, 2024).
liver disease (1 paper, 2020). "Absence of Alox12/15 aggravated parameters of liver disease, increased hepatic immune cell infiltration in AH, and elevated systemic neutrophils as a marker for systemic inflammation." (PMID 32760397, 2020).
lupus (1 paper, 2025).
myeloproliferative disease (1 paper, 2024). "The Alox15 gene, an ortholog of the human ALOX12 gene, develops the myeloproliferative disease characterized by pancytopenia attributed to hematopoietic stem cell dysfunction at the asymptomatic stage, followed by an abnormal expansion of myeloid cells in the spleen and bone marrow." (PMID 38731802, 2024).
non-alcoholic steatohepatitis (1 paper, 2025). "IMA-1 targets ALOX12 to inhibit lipid uptake and ameliorate non-alcoholic steatohepatitis." (PMID 41561171, 2025).
Perthes disease (1 paper, 2023). "Notably, the DEGs identified in the rabbit model of Perthes disease in this study correlated with genes previously reported to be involved in inflammation [IL-6 and HIFa] and angiogenesis [PTGER2 and ALOX12] in Perthes disease." (PMID 37303951, 2023).
pulmonary edema (1 paper, 2024). Accumulation of fluid in the lung tissues causing disturbance of the gas exchange that may lead to respiratory failure. "Notably, rHMGB1 treatment exacerbated lung injury in Alox12-KO mice after lung IR, as evidenced by increases in lung injury scores, airway resistance, PaCO2, microvascular permeability, and pulmonary edema and decreases in airway compliance, PaO2, and survival." (PMID 39268501, 2024).
pulmonary hypertension (1 paper, 2022). Increased pressure within the pulmonary circulation due to lung or heart disorder. "ALOX12 has been implicated in the regulation of angiogenesis in other organs and in maladaptive vascular remodeling in pulmonary hypertension." (PMID 36239312, 2022).
schizophrenia (1 paper, 2010). A major psychotic disorder characterized by abnormalities in the perception or expression of reality. "To test this hypothesis, we investigated the single nucleotide polymorphisms (SNPs) of the ALOX12 gene in schizophrenia patients." (PMID 20626912, 2010). "Therefore, we investigated single nucleotide polymorphisms (SNP) of the ALOX12 gene in schizophrenia, recruiting patients with schizophrenia (n = 289) and normal controls (n = 306) from a Korean population." (PMID 20626912, 2010). "However, research has yet to show the genetic association between ALOX12 and schizophrenia." (PMID 20626912, 2010). "Therefore, we hypothesized genetic variances of the ALOX12 gene might be associated with schizophrenia." (PMID 20626912, 2010). "Genotype distribution of SNPs of the ALOX12 gene among schizophrenia patients in a Korean population." (PMID 20626912, 2010). "Genotype distribution of ALOX12 gene SNPs among schizophrenia patients in a Korean population." (PMID 20626912, 2010). "However, no research has yet shown the association between ALOX12 and schizophrenia." (PMID 20626912, 2010). "Consequently, we suggest that SNPs of the ALOX12 gene might be associated with schizophrenia and negative symptoms in this Korean population." (PMID 20626912, 2010). "We conclude that rs1126667 and rs1042357 of the ALOX12 gene correlate with schizophrenia in a Korean population, and rs434473 correlates with negative symptoms in schizophrenia." (PMID 20626912, 2010).
steatosis (1 paper, 2025). Increased lipid within the cytoplasm of cells. "We found that the elevated iron concentrations in serum and liver tissues, increased PTGS2 and ALOX12 expression, and higher hepatic MDA levels were observed in Insig2 KO mice following steatosis I/R injury compared to WT mice." (PMID 40169542, 2025).
Thrombocytopenia (1 paper, 2022). A reduction in the number of circulating thrombocytes. "A large number of research studies prove that C. papaya leaf has an influential role against thrombocytopenia by targeting the ALOX-12, PTFAR, and CD110 receptor genes." (PMID 35566112, 2022).
Thromboembolism (1 paper, 2021). The formation of a blood clot inside a blood vessel that subsequently travels through the blood stream from the site where it formed to another location in the body, generally leading to vascular occlusion at the distant site. "Mice models lacking ALOX12 (P-12LO) exhibit a selective modulatory role for P-12LO in the ADP-induced pathway of platelet aggregation in mice, and increased mortality in an ADP-induced mouse model of thromboembolism." (PMID 34091768, 2021).
toxoplasmosis (1 paper, 2017). A parasitic disease contracted by the ingestion or fetal transmission of toxoplasma gondii. "Similarly, the ALOX12 gene, which encodes the enzyme arachidonate 12-lipoxygenase, has allelic variants associated with toxoplasmosis and ALOX12 knockdown prevents Toxoplasma tachyzoites from proliferating likely by increasing host cell death." (PMID 28278184, 2017).
tuberculosis (1 paper, 2017). A chronic, recurrent infection caused by the bacterium Mycobacterium tuberculosis. "A genetic polymorphism associated with elevated ALOX12 expression is associated with an enhanced risk of tuberculosis." (PMID 29085351, 2017). "The presence of 12/15-lipoxygenase (ALOX12) products in cavitary tuberculosis lesions is correlated with airway neutrophilia and bacterial burden." (PMID 29085351, 2017).
tumor (60 papers, 2011 to 2025). "Ex vivo treatment with 12(S)-HPETE induces the cell death of aberrant hematopoietic progenitor cells from Alox15-deficient mice, suggesting the tumor-suppressive function of ALOX12." (PMID 38731802, 2024). "ALOX12−/− deficiency significantly protected mice from radiation-enhanced tumor colonization, with the number of tumor nodules similar between irradiated and unirradiated ALOX12−/− mice." (PMID 35158337, 2022). "GSEA enrichment analysis suggested that ALOX12 was tightly associated with tumor occurrence and metastasis pathways such as ECM receptor interaction, NOTCH signaling pathway, pathways in cancer, and positive regulation of GTPase activity." (PMID 35833141, 2022). "On the basis of GSEA and GSVA results, we observed that ALOX12 expression was tightly associated with tumor immune-related pathways." (PMID 35833141, 2022). "Prognostic analysis and in vitro experiments further demonstrated that ALOX12 was closely associated with the prognosis, tumor proliferation, invasion, and metastasis." (PMID 35833141, 2022). "ALOX12 and its metabolite, 12S-hydroxyeicosatetraenoic acid, have been implicated in influencing tumor transformation and progression." (PMID 34249719, 2021). "Finally, the risk score was calculated by the following formula: tumor-associated endothelial signature score = 0.180855332*ADD1 + 0.059530341*ALOX12 + 0.145361104 *CXCL10 - 0.081730252*F2RL1 + 0.001225741*ITGAX − 0.004914148*MET." (PMID 37719845, 2023). "Furthermore, ALOX12 protein expression was assessed in clinical OC tissues, and was found to be positively associated with tumor lymph nodes and distant metastasis." (PMID 36851083, 2023). "Furthermore, tumor-associated ALOX12 missense mutations lose their lipoxygenase activity and ability to induce ferroptosis." (PMID 33182266, 2020). "The overexpression of ALOX12 has been addressed in several tumor tissues, including prostrate and colorectal cancer." (PMID 39766798, 2024). "SLC7A11, as a key repressor of ferroptosis, is upregulated in tumors and can interact with ALOX12 to promote tumor progression." (PMID 36846713, 2023). "Genetic inhibition of ferroptosis by Alox12/15 deletion or Acls4 deletion, or inhibitors of ferroptosis, erased the immunosuppressive effect of tumor PMN-MDSCs in different murine models and patient samples." (PMID 36813764, 2023). "At present, relevant studies have confirmed that the expression of ALOX12 can reasonably predict the prognosis of patients, and ALOX12 can be used as a predictor of tumor prognosis." (PMID 36309489, 2022). "GSEA, GSVA, and multi-omics data analysis demonstrated that high ALOX12 expression patients were not only tightly related to tumor development and metastasis but also possessed potential benefits for chemotherapy." (PMID 35833141, 2022).
tumor (continued). "The results exhibited that high ALOX12 expression predicted a higher immune infiltration and better immunotherapy response, which was further validated in Tumor Immune Dysfunction and Exclusion (TIDE) and Subclass Mapping (SubMap) methods." (PMID 35833141, 2022). "Together, this study demonstrates the critical role of senescence in mediating radiation-enhanced tumor growth and identifies Alox12 as an important player in this phenomenon." (PMID 35158337, 2022). "GSVA demonstrated that most of the tumor-related pathways exhibited significant differences between the high and low ALOX12 expression groups, further validating the important potential functions of ALOX12 in tumors." (PMID 35833141, 2022). "Inhibition of ALOX12 abrogates TPCI-mediated tumor growth suppression in both in vitro and in vivo models." (PMID 36517470, 2022). "ALOX12 is an enzyme involved in arachidonic acid metabolism that promotes tumor progression and angiogenesis." (PMID 36239312, 2022). "Together, these data support a model whereby Mll4 is critical for the activation of key lipoxygenase genes such as Alox12 to promote both epidermal differentiation and barrier formation and, in turn, tumor suppression via ferroptosis." (PMID 34890228, 2021). "Six genes (DNAJB6, RB1, VIMP/SELENOS, STEAP3, BACH1, and ALOX12) had a consistent mRNA expression level in tumor samples and prognosis in the univariate Cox analysis." (PMID 34075060, 2021). "It has been confirmed that ALOX12 has the capability of mediating inflammation, cell migration, apoptosis, and tumor cell proliferation." (PMID 34291083, 2021). "As shown by IHC staining, the expressions of ALOX15 and ALOX15B were strikingly down-regulated, while ALOX5 and ALOX12 were strikingly up-regulated in tumor, compared with those in surrounding tissue." (PMID 31528237, 2019). "SW480 and the well-differentiated CaCo2 cells (both derived from primary tumour sites) express less ALOX12 and produce only half the amount of 12(S)-HETE as compared to SW620 cells." (PMID 28013338, 2017). "Furthermore, ALOX12 expression restrains the growth, infiltration, and movement of cancerous cells, and additionally impedes tumor expansion in living organisms." (PMID 41210681, 2025). "Moreover, the expression of ALOX12 also heightens the responsiveness of tumor cells to ferroptosis initiators, consequently enhancing the frequency of tumor cell demise." (PMID 41210681, 2025).
tumor (continued). "The ALOX12 gene may function as a suppressor of bone marrow blastogenesis and tumor progression in MDS." (PMID 38731802, 2024). "A similar hypothesis has been proposed in relation to ALOX12 inhibition in tumor cells from cervical squamous cell carcinoma, head and neck squamous cell carcinoma, esophageal squamous cell carcinoma and acute myeloid leukemia." (PMID 38612771, 2024). "In addition, high expression in tumor tissues makes ALOX12 easier to be detected, increasing its utility for clinical applications." (PMID 35833141, 2022). "Interestingly, the tumor-derived missense ALOX12 mutants lost their lipoxygenase activity and ferroptosis-inducing capacity, suggesting a potential role of inadequate ferroptosis-mediated tumor suppression." (PMID 32718025, 2020). "We discovered that ALOX12 expression was substantially higher in malignant samples than in adjacent samples, and was linked to lymph node and distant metastasis, but not to patient age or tumor size in OC samples." (PMID 36851083, 2023). "However, inhibition of ALOX12 activity by ML355 diminished the anti-tumor efficiency of TPCI." (PMID 36517470, 2022). "This suggests potential modulation by tumor-specific factors such as epigenetic states or co-regulators, warranting further investigation into auxiliary mechanisms fine-tuning SLC7A11 and ALOX12 activity." (PMID 40696490, 2025). "Studies using single‐cell RNA sequencing have indicated that ferroptosis‐related genes such as ALOX12 and SLC7A11 show differential expression patterns across distinct tumor regions, contributing to the heterogeneous response to FINs." (PMID 40919133, 2025). "Biologically, SLC7A11 knockdown promotes ALOX12’s lipoxygenase activity to increase the peroxidation of PUFA-containing phospholipids, ultimately inducing ferroptosis and thereby inhibiting tumor progression." (PMID 40696490, 2025). "ALOX12 is a tumor suppressor gene, but it is highly expressed in tumor tissues by RT-qPCR, which may be due to the fact that this gene can enhance the occurrence of tumor suppressor pathway through over-expression, thus achieving the function of tumor suppressor." (PMID 38903709, 2024). "Because our results indicated that both ALOX12 and FKBP5 gene expression induced cellular death and inhibited the tumor growth and invasion ability of cancer cells, we aimed to examine the molecular mechanism of these antitumor effects." (PMID 39766798, 2024). "Compared to that in peritumor tissues, the expression of ferroptosis-inducing genes, including PTGS2, ALOX12, TFR2, and HMOX1, was decreased in tumor tissues, whereas ferroptosis-suppressor genes, including SLC7A11 and GPX4, were increased." (PMID 37554285, 2023). "Moreover, our results demonstrated that ALOX12 statuses were positively associated with node metastasis (p < 0.001), distant metastasis (p < 0.001), and clinical stages (p < 0.05), but not with age or tumor size." (PMID 36851083, 2023).